TNFAIP8 (TNF alpha induced protein 8)
Diseases named in the same sentence as TNFAIP8 in open-access papers (continued):
Sharing a sentence is not in itself a finding about the gene and the disease.
cancer (continued). "However, the individual role of TNFAIP8 isoforms in cancer cell biology needs to be further investigated." (PMID 29928491, 2018). "Because TNFAIP8 is an oncogenic molecule that dysregulates the expression of multiple cell-cycle-related proteins and promotes cancer cell growth, and therefore we hypothesized that TNFAIP8 may promote cancer cell growth by inducing autophagy." (PMID 29928491, 2018). "Overexpression of TNFAIP8 has been reported in several cancers." (PMID 28152516, 2017). "The tumor necrosis factor-alpha-induced protein 8 (TNFAIP8) gene family has recently come to prominence as a regulator of several physiological and pathological processes, in particular with relation to immunity and cancer." (PMID 28658311, 2017). "The expression of TNFAIP8 has been identified in various types of human cancer." (PMID 25936980, 2015). "TNFAIP8 overexpression has frequently been observed in several types of cancer tissues, suggesting that TNFAIP8 may be significant in oncogenesis." (PMID 24137373, 2013). "The overexpression of TNFAIP8 in cancer cells may inhibit TNF-induced apoptosis by inhibiting caspase-8 and caspase-3 activity, while the depletion of TNFAIP8 enhances cell death." (PMID 24137373, 2013). "Experimental evidence also supports the theory that TNFAIP8 is an oncogene in human cancers." (PMID 24137373, 2013). "Recent studies have revealed that tumour necrosis factor alpha-induced protein 8 (TNFAIP8) is involved in various biological and pathological processes of cells, but their underlying mechanisms in processes ranging from cancer development to drug resistance have not been fully elucidated." (PMID 30064446, 2018). "However, the mechanisms underlying TNFAIP8-mediated cancer development and its downstream pathways have not yet been systematically explored." (PMID 30064446, 2018). "In order to better understand the molecular aspects, biological functions, and potential roles of TNFAIP8 in carcinogenesis, in this review, we focused on the expression, regulation, structural aspects, modifications/interactions, and oncogenic role of TNFAIP8 proteins in human cancers." (PMID 30586922, 2018). "Most reports believe that TNFAIP8 and TIPE3 have antiapoptotic and tumorigenesis effects, while TIPE1 and TIPE2 have pro-apoptotic and antitumor effects in most cancers." (PMID 34925463, 2021). "Besides, subgroup analysis revealed that TNFAIP8 rs1045242 polymorphism increased the risk of OC in patients with age ≤ 54 years old, smoking history, no complication, and no family cancer history, uncovering that individuals exposed to these factors are more susceptible to OC." (PMID 32821249, 2020). "Additionally, we showed that TNFAIP8, the IL-6 cytokine receptor, and IL-6-activated STAT3 pathway activity increased following FFAR2 reduction in the all cancer group." (PMID 37296861, 2023). "The expression pattern of the various TNFAIP8 isoforms in cancer cells has not been previously investigated." (PMID 29928491, 2018). "The TNFAIP8 gene was subsequently shown to be an early responder to TNF-alpha stimulation in human umbilical vein endothelial cells and to be expressed in variety of normal tissues and cancer cell lines." (PMID 28658311, 2017). "Additionally, TNFAIP8 was highly expressed in the cytoplasm in cancer tissues compared to levels in adjacent noncancerous tissues." (PMID 32226521, 2020). "Although TNFAIP8 isoform 2 is predominantly expressed in several cancers, the roles of individual TNFAIP8 isoforms are not clear so far and therefore, in the current review, we focused on the regulation, structure, interactions, and biological functions of TNFAIP8 proteins in human cancer." (PMID 30586922, 2018).
infection (8 papers, 2015 to 2025). The state of being infected such as from the introduction of a foreign agent such as serum, vaccine, antigenic substance or organism. "NF-κB is instrumental in regulating the immune response to infection, while tumor necrosis factor α-induced protein 8 (TNFAIP8) palys an essential role in regulating inflammation, autoimmunity, and maintaining cellular homeostasis." (PMID 40270019, 2025). "In the current review, we focus on the role of TNFAIP8 in cell signaling inflammation, infections, immune regulation, and related diseases." (PMID 31723944, 2019). "Infection with TNFAIP8-expressing lentivirus increased TNFAIP8 expression effectively." (PMID 32795319, 2020). "Research in humans and murine models using infection with S. aureus as phenotypic trait have suggested different positional candidate genes, e.g., SEH1L, TNFAIP8, KLK, and CDON." (PMID 26612358, 2015). "Looking at the cytokine levels, there was observed up regulation of pro-inflammatory TNF-α induced proteins (TNFAIP6 [log2FC 2.6], TNFAIP8 [log2FC 5.3]) involved in systemic inflammation; and also, elevation of interleukins IL21 (Log2FC 3.7) and IL1 receptor (Log2FC 2.0) that respond to infection." (PMID 32000760, 2020).
adenocarcinoma (1 paper, 2018). A common cancer characterized by the presence of malignant glandular cells. "The univariate analysis results revealed that advanced pTNM stage, positive lymph nodes and higher TNFAIP8 expression were indicators of poor OS; in addition, the adenocarcinoma subtype, advanced pTNM stage, positive lymph nodes and high TNFAIP8 expression were predictors for poor DFS." (PMID 30064446, 2018).
metabolic disease (1 paper, 2024). A congenital disorder (due to inherited enzyme abnormality) or acquired (due to failure of a metabolically important organ) disorder resulting from an abnormal metabolic process. "Key genes, including PLA2G12A, PLA2G6, and TNFAIP8, offer potential therapeutic targets for metabolic diseases." (PMID 39277575, 2024).
TNFAIP8 also shares sentences with these, for which no sentence is quoted: gastric adenocarcinoma (2 papers); immune dysfunction (2); Parkinson disease (2); acute monocytic leukemia (1); alcoholic fatty liver disease (1); asthma (1); atopic eczema (1); autoimmune thyroiditis (1); cerebrovascular disease (1); Cirrhosis (1); clear cell renal cell carcinoma (1); endocarditis (1); endometrial tumor (1); fibrosis (1); follicular lymphoma (1); glioblastoma multiforme (1); inflammatory bowel disease (1); invasive ductal breast carcinoma (1); MALT lymphoma (1); neuroblastoma (1); non-Hodgkin lymphoma (1); osteosarcoma (1); ovarian serous cystadenocarcinoma (1); pancreatic adenocarcinoma (1); pancreatic ductal adenocarcinoma (1); prostatic adenocarcinomas (1); renal cell carcinoma (1); testicular germ cell tumor (1); thymoma (1); thyroid carcinoma (1).
A further 1 disease shares a sentence with TNFAIP8 in 1 paper.